BTN3A1 (butyrophilin subfamily 3 member A1)
Diseases named in the same sentence as BTN3A1 in open-access papers (continued):
Sharing a sentence is not in itself a finding about the gene and the disease.
tumor (continued). "To associate physiologic relevance of anti-tumor activity and the suppressive effect of Vδ2+ T cells ex vivo, we first exposed untouched Vδ2+ T cells to BTN3A1-expressing tumor cells (U251 or SK-Mel-28) and consecutively co-cultured them with autologous αβ T cells." (PMID 31982940, 2020). "The activation of Vδ2pos T cells relies on the recognition of non-peptidic compounds (i.e. microbial or stress- or tumor-induced “phosphoantigens”) in association with butyrophilin 3A1 (BTN3A1 also known as CD277)." (PMID 31829255, 2019). "Besides the TCR interactions with phosphoantigens/BTN3A1 complexes, several Natural Killer Receptors (NKRs) are involved in triggering the anti-tumor functions of Vδ2pos T cells, with the C-lectin type NKG2D playing a major role." (PMID 31829255, 2019). "Importantly, the injected tumor lesions also express genes whose protein products are the antigenic ligands for γδ T cells (BTN3A1 and MICB), and the cytokines that are the typical products of activated γδ T cells." (PMID 28424760, 2017). "WiDr tumor cells have a higher cell surface expression of BTN3A1 compared to the WM9 and HAP1 cell lines, which could explain the higher killing percentage and significant increase of CD25 and CD69 on the challenged Vδ2 T cells because BTNs are well described stimulants of the Vδ2 TCR." (PMID 38426099, 2024). "Finally, since BTN2A1 and BTN3A1 are not only expressed on tumor cells but also on Vg9Vd2 T cells and other T cells, the potential for (self-)elimination of immune cells should be taken into consideration when evaluating the safety profile and the presence of immune populations in peripheral blood." (PMID 39144149, 2024). "According to the current model, microbe- or tumour-derived pyrophosphates bind to the intracellular B30.2 domain of BTN3A1 which then interacts with BTN2A1 to induce a conformational alteration of the extracellular BTN3A1/2A1 complex which is recognized by the γδ TCR." (PMID 38090581, 2023). "In addition, a more convenient method to detect BTN2A1 and BTN3A1 expression would be necessary.Dysregulation of the mevalonate pathway is common in tumor cells, leading to the accumulation of both DMAPP and IPP, which could be recognized by Vγ9Vδ2 T cells." (PMID 37770968, 2023). "Hence, BTN3A1 may be an attractive immune target for intervention to orchestrate effective and coordinated γδ and αβ T-cell anti-tumor responses." (PMID 35880177, 2022). "In addition to direct tumor‐killing and antigen presentation, we also uncover another synergistic mechanism of pVγ9Vδ2/αβ T cell combinatorial therapy, through which pVγ9Vδ2 T cells reverse BTN3A1‐mediated αβ T cell inhibition by competitively binding to BTN3A1 expressed by CC cells." (PMID 40091603, 2025). "These tumor-infiltrating DCs exhibit high PD-L1, CD277 (BTN3A1) expression, and Arginase-1 activity, and they release immunoregulatory cytokines that collectively suppress T-cell priming." (PMID 41470247, 2025). "Due to dysregulation of the mevalonate pathway, phosphoantigen levels can accumulate in tumor cells resulting in elevated, Vδ2 TCR activating BTN3A1/3A2 complexes on the cell surface." (PMID 38426099, 2024). "We also observed increased expression levels of immune‐related genes, such as SLAMF7, TNFSF8, BTN3A1, CD2, LGALS9, PRF1, and MX2, in tumor samples from the MT group of the Local‐SCLC cohort." (PMID 38125769, 2023). "IHC staining conducted on matched tumor tissue samples from PTCs in the SAT group confirmed the elevated expression levels of BTN2A1 and BTN3A1." (PMID 37770968, 2023). "Since Vγ9Vδ2 T cells can recognize tumor cells expressing BTN2A1 and BTN3A1, we compared the expression of these two molecules in different GBM cell lines by flow cytometry and matched tumor samples of PTCs using IHC staining." (PMID 37770968, 2023).
tumor (continued). "Several studies have shown that Vγ9Vδ2 T cells recognize phosphoantigen depending on the butyrophilin 3A1 (BTN3A1, also known as CD277), a member of the B7 superprotein family, expressed on antigen-presenting cells (APCs) and tumor cells." (PMID 32413966, 2020). "In addition, both γδ T and NK cells degranulated and consistently induced lysis in a panel of NB cell lines and patient-derived 3D tumor spheres expressing B7H6, calreticulin, HA-TAG, BTN2A1, and BTN3A1/2/3 consistently." (PMID 41694338, 2026). "HCC is infiltrated by non-conventional T cells, which identify tumor antigens such as butyrophilin subfamily 3 member A1 (BTN3A1), a ligand activating γδ T cell receptors, without major histocompatibility complex (MHC) restriction." (PMID 40869156, 2025). "In addition, we found that IFN‐γ‐induced BTN3A1 expression in CC cells was dependent on JAK‐STAT1 signaling pathway, which is reminiscent of the mechanism of IFN‐γ‐induced PD‐L1 expression in tumor cells." (PMID 40091603, 2025). "Nevertheless, it seems that elevated levels of PAg in tumor cells are not sufficient to produce the full activation of BTN3A1, therefore strategies to increase PAg would be necessary." (PMID 39144149, 2024). "However, there are also regions in the tumor that only expressed BTN2A1, BTN3A1/PD-L1 or BTN2A1/BTN3A1/PD-L1." (PMID 38077396, 2023). "BTN3A1 is barely detectable in situ and mainly in the cytoplasm of cultured CRC-TAF, possibly needing an undefined signal (e.g., an inflammatory cytokine) to be expressed by tumor stroma." (PMID 36765569, 2023). "On the other hand, Payne and colleagues reported that, in its spontaneous conformation without BTN2A1, BTN3A1 inhibited tumor-reactive αβ T cell activation." (PMID 37629075, 2023). "We have recently developed a novel T cell engager concept by utilizing γ9δ2TCR as tumor targeting domain, named gamma delta TCR anti-CD3 bispecific molecule (GAB), targeting the phosphoantigen-dependent orchestration of BTN2A1 and BTN3A1 at the surface of cancer cells." (PMID 36685546, 2022). "Radiotherapy moderately suppressed control group tumor growth compared with non-radiotherapy treatment (p < 0.01) while prominently inhibiting the growth of BTN3A1-knockdown tumors (p < 0.001)." (PMID 36418890, 2022). "Here, we found that butyrophilin subfamily 3 member A1 (BTN3A1) is upregulated in ESCC tumor tissues compared with nontumor tissues." (PMID 36418890, 2022). "We collected samples from 118 patients and examined BTN3A1 expression in tumor and adjacent nontumor tissues by performing immunohistochemical (IHC) staining." (PMID 36418890, 2022). "Intriguingly, untouched Vδ2+ T cells do not suppress autologous αβ T cells even after exposure to BTN3A1+ tumor cells." (PMID 31982940, 2020). "BTN3A1 is the main isoform of the butyrophilin 3A (BTN3A, CD277) family and can directly bind phosphor-antigens, activating the Vγ9Vδ2 T cells in colorectal cancer microenvironment for the anti-tumor response of zoledronate." (PMID 33042828, 2020). "This requires BTN3A1 activation on tumor cells as pre-incubation of a BTN3A1 agonist with the effector T cells before addition to the target cells does not lead to tumor cell lysis, even at high T-effector: cancer cell ratios." (PMID 32235616, 2020). "Regulation of BTN3A1 stability together with protein trafficking and expression of the transporter ABCA1 within tumor microenvironment, as shown for doxorubicin, may be crucial to trigger optimal cross-talks between DCs and γδ T cells." (PMID 32435249, 2020). "BT3 molecules (BTN3A1/BT3.1, BTN3A2/BT3.2 and BTN3A3/BT3.3) are known to be expressed on endothelial cells, in the membrane layer surrounding milk fat-secreting droplet from mammary epithelial cells, on immune cells, and on some tumor cell lines." (PMID 22685580, 2012). "Importantly, P4 treatment induced NLRC5 and BTN3A1 co-expression in tumor tissue in our mice experiments compared to those without P4 treatment." (PMID 36632221, 2023).
tumor (continued). "No BTN2A1 or BTN3A1 expression was detected in tumor-adjacent tissue or normal brain tissue." (PMID 37770968, 2023). "To date, the mode of BTN3A1-mediated tumor cell death has not been studied." (PMID 36418890, 2022). "The BTN3A1 protein level was evaluated in ESCC tumor and nontumor tissues." (PMID 36418890, 2022). "Similarly, the expression of BTN3A1, CSF2RB, GIMAP7, GZMB, HCLS1, LCP2, and SELL was positively correlated with the infiltration of B cells, CD8+ T cells, CD4+ T cells, neutrophil, and DCs, but was negatively correlated with the tumor purity." (PMID 33042828, 2020). "Since direct contact with BTN3A1-expressing tumor cells alone does not bestow suppressive activity onto Vδ2+ T cells, further studies are needed to comprehensively identify what exactly activates Vδ2+ T cells and how activation translates into various specific effector functions." (PMID 31982940, 2020). "Thus, the expression pattern, regulatory mechanism, and αβ T cell inhibiting effect of BTN3A1 make it highly similar to PD‐L1, further elaborating the notion that BTN3A1 expressed by tumor cells may be another immune checkpoint molecule rather than merely activate Vγ9Vδ2 T cells with BTN2A1 in CC." (PMID 40091603, 2025). "It is noteworthy that CEA.CAR-γδ T cells produced IFN-γ upon incubation with CEA+ (MC32a), but not CEA- tumor (MC38) cell lines which originated from mice and do not express BTN3A1/2A1." (PMID 37446055, 2023). "Vγ2Vδ2 T cell are stimulated by a wide array of tumors because recognition does not require neoantigens or tumor-specific proteins or MHC expression but instead is dependent on alterations in isoprenoid metabolism and expression of BTN3A1." (PMID 28239463, 2017).
cancer (37 papers, 2018 to 2025). A tumor composed of atypical neoplastic, often pleomorphic cells that invade other tissues. "BTN3A1 is closely associated with cancers, and its expression is strongly correlated with the clinical prognosis of cancers." (PMID 40959207, 2025). "Although relatively few antigens have been associated with the recognition of cancer cells by γδ T cells, it is now known that the phosphoantigen sensors BTN3A1 or CD277 play a key role in the TCR-dependent activity of these cells." (PMID 39063202, 2024). "At the same time, in a variety of human cancers, BTN3A1 shows an excellent diagnostic value and can be used as a target for predicting drug resistance and judging the prognosis of patients." (PMID 36033440, 2022). "In this study, 8 databases comprising 33 cancer types and 86 733 cases were accessed to analyze the expression, mutation, enrichment of related signal pathways of BTN3A1, and its relationship with immune cell infiltration and the prognosis of cancer patients." (PMID 34293829, 2021). "As previous work also identified somatic mutations of NLRC5 in 4.8% of EBV-positive NPCs 40, but whether these mutations affect BTN2A1 and BTN3A1 expression remains to be investigated in clinical NPC cancers." (PMID 36632221, 2023). "We showed that BTN3A1 mutations are found in several cancers at the coding regions of each domain." (PMID 34293829, 2021). "Vγ9Vδ2 T cells exhibit a consistent specificity for the BTN2A1-BTN3A1-BTN3A2 complex, and elevated expression of BTN3A1 (CD277) can be observed within malignant tumors." (PMID 38311633, 2024). "Recently, these data were confirmed and extended through a genome-wide CRISPR screen demonstrating the importance of endogenous NLRC5 for the expression of BTN3A1–3, and for cancer cells’ recognition and killing by Vγ9Vδ2 T cells." (PMID 39035010, 2024). "Here, we discuss our current understanding of BTN and BTNL biology, with a particular focus on BTN3A1, and potential therapeutic implications for cancer." (PMID 37240071, 2023). "In a critical advance in targeting BTN3A1 in the setting of cancer, Imcheck Therapeutics has developed a BTN3A-specific antibody, ICT01, a humanized version of clone 7.2 that recognizes an epitope within BTN3A1 which overlaps with clone 20.1." (PMID 37240071, 2023). "S1D), bone metastatic samples presented high expression of BTN3A1 in most of the cores, with the majority of cancer cells (≥50%) staining positively for BTN3A1 expression in 63% of the cores analyzed." (PMID 37134157, 2023). "Recent studies have shown that BTN3A1 is essential to the prenyl pyrophosphate-mediated activation of Vγ9/Vδ2 T-cells and plays a fundamental function in human cancer immunotherapy." (PMID 36211333, 2022). "BTN3A1 was mainly located in the cytoplasm and only a few were distributed on the cell surface, and its expression was significantly increased in cancer tissues." (PMID 36418890, 2022). "We showed that BTN3A1 was expressed in most cancers, and its expression level was strongly correlated with clinical outcome of 13 cancers." (PMID 34293829, 2021). "In these cancer types, the co‐expressed genes of BTN3A1 were mainly distributed in immune regulation‐related pathways, such as differentiation and activation of immune cells, cytokine secretion, and immune response." (PMID 34293829, 2021). "In this study, we performed Pan‐cancer analysis to evaluate the role for BTN3A1 to play in tumorigenesis and reported that there was a significant differential expression pattern of BTN3A1 among the 33 cancer types." (PMID 34293829, 2021). "We employed the Kaplan–Meier plotter database to evaluate the relationship between BTN3A1 expression level and patient outcome in multiple cancer types." (PMID 34293829, 2021). "Here, the expression of BTN3A1 in cancers was analyzed in eight databases comprising 86 733 patients of 33 cancers, and the findings were validated in patient samples and cell models." (PMID 34293829, 2021).
cancer (continued). "BTN2A1, together with BTN3A1, is present on the surface of antigen-presenting cells and cancer cells, and after the internal domain of BTN3A1 binds phosphoantigens, conformational changes in both molecules occur, allowing BTN2A1 to bind to the Vγ9 region of the TCR γδ." (PMID 40276509, 2025). "Third, combination of BRRF1 and LMP1 transduction could be attempted in various cancers to determine if they will achieve high expression of BTN2A1/BTN3A1 proteins, especially among those NPC cell lines unresponsive to BRRF1 alone." (PMID 39769218, 2024). "Thus, BTN2A1 and BTN3A1 molecules are particularly important for consideration in studying the effects of Vγ9Vδ2 T cells in immunotherapy against cancer." (PMID 39769218, 2024). "While dysregulated expression has been observed on the surface of malignant cells and infiltrating leukocytes—most notably dendritic cells—in both malignancies, the mechanisms driving aberrant overexpression of BTN3A1 in cancer remain unknown." (PMID 37240071, 2023). "However, its role in these tumors is unclear, and the prognostic role of BTN3A1 in different cancers varies substantially." (PMID 36418890, 2022). "RhoB can also regulate the membrane mobility of BTN3A1 on cancer cells." (PMID 34149914, 2021). "Our results demonstrated that BTN3A1 was perturbed in cancers and this gene might have an important role in cancer development and progression." (PMID 34293829, 2021). "Importantly, in the presence of soluble BTN3A1 agonists, Vγ9Vδ2 T cells have been shown to be highly effective in cancer cell killing in co-culture experiments at various target: effector ratios." (PMID 32235616, 2020). "Clarifying the roles of these molecules in cancer and, subsequently, their potential to function as immunotherapeutic targets may drive the development of more effective cancer immunotherapies, as discussed in the case of BTN3A1 below." (PMID 37240071, 2023). "We also demonstrated the involvement of BTN3A1 and BTN2A1, crucial molecules for γδ T cell activation, as well as differential expression of PDL1/CD274 in cancer, E6/E7+ and healthy organoids." (PMID 38090581, 2023). "For single immune checkpoint gene, the immune stimulator HMGB1 correlated positively with KIF11 in all human cancer types, and TNFSF4, BTN3A1, BTN3A2, and ENTPD1 correlated positively with KIF11 in most human cancer types." (PMID 36742345, 2022). "While BTN3A1 has been extensively investigated in cancers and γδ T cells, studies in CD4+ T cells and SLE are absent." (PMID 40959207, 2025). "Additionally, DBF4B showed a positive correlation with HMGB1, BTN3A1, and VEGFA across various cancers." (PMID 40535802, 2025). "Antitumor cytotoxic functions and αβ T cells activating functions of Vγ9Vδ2 T cells are shown to be abrogated by BTN3A1 expression by the cancer epithelial cells in its spontaneous conformation without BTN2A1122." (PMID 38703051, 2024). "More importantly, the expression of PIK3R4 in DLBCL was correlated with the immune cell content in the cancer microenvironment, CD8(+) T-cell and neutrophil infiltration and the levels of several immune checkpoint molecules, including BTN3A2, BTN3A1, PRF1, CXCL9, PDCD1, and TIGIT." (PMID 37670973, 2023). "However, our blocking studies using inhibitory antibodies against BTN2A1 and BTN3A1 clearly indicated the significance of these BTN molecules in triggering the cytotoxic activity of γδ T cells against HPV+ and cancer organoids., in line with previous reports." (PMID 38090581, 2023). "ENST00000311534 was significantly correlated with HMGB1, ENST00000326094 was significantly correlated with BTN3A1, CD160, TGFBR1, and IL6R, and ENST00000375991 was significantly correlated with CD276, ENTPD1, HMGB1, TLR4, KDR, and TGFBR1 among these 33 immune genes in more than 20 cancer types." (PMID 39766805, 2024).
cancer (continued). "Such strategies might include (but are not restricted to) sensitizing cancer cells with γδ T cell activating drugs like zoledronate, bispecific γδ T cell engagers, or agonistic anti-BTN3A1 antibodies." (PMID 38090581, 2023). "BTN3A1-stimulating antibodies or IPP transformed the immunosuppressive molecule conformation of BTN3A1 into an immunostimulatory one and elicited coordinated restoration of αβ T cell effector activity and BTN2A1-dependent γδ T lymphocyte cytotoxicity against BTN3A1+ cancer cells." (PMID 37629075, 2023). "IPP can also be secreted from cancer cells and APCs into the extracellular environment to activate Vγ9Vδ2 T cells, and this mechanism was shown to involve the ATP-binding cassette transporter A1 (ABCA1) in cooperation with apolipoprotein A-I (apoA-I) and BTN3A1." (PMID 34944832, 2021). "We were thereby able to show a positive correlation between BTN3A1, MAP3K3, and UBA7 expression and the majority of immune infiltrates (B cells, CD4 + T cells, CD8 + T cells, macrophages, and neutrophils) in most cancer types, and a negative correlation with myeloid dendritic cells." (PMID 39127727, 2024).